IL1B (interleukin 1 beta)
Diseases named in the same sentence as IL1B in open-access papers (continued):
Sharing a sentence is not in itself a finding about the gene and the disease.
eczema (10 papers, 2016 to 2025). "Huangbo has also become a staple for eczema treatment, as it could decrease mRNA expressions of proinflammatory cytokines (like IL-1β, TNF-α, IL-17, IL-4, and IL-13)." (PMID 41311842, 2025). "Under the action of allergens in the skin system, numerous inflammation-mediated factors, such as TNF-α, IL1β, and IL-4, are secreted during epidermal keratinization, all of which interact with each other in the pathogenesis of eczema, thus influencing the development and prognosis of the disease." (PMID 35907999, 2022). "In eczema, TNF-α, IL-1β, and IL-4 expression increases, binding to receptors activates NF-κB, stimulating inflammatory mediator production (e.g., TNF-α, IL-1β, and IL-4), creating a positive feedback loop." (PMID 40933470, 2025). "CTGO significantly improved the skin surface and histopathological characteristics of eczema-affected rats, downregulated the expression of IL-4, TLR4, NF-κB (p65), IL-1β, and TNF-α, and upregulated the expression level of IFN-γ." (PMID 35907999, 2022). "ELISA and Western blotting analyses revealed that SYXL alleviated eczema-like skin lesions induced by DNCB in animal models, reversed histopathological abnormalities, curbed the expression of pro-inflammatory cytokines IL-1β, IL-6, and TNF-α, and inhibited the phosphorylation of JAK2 and STAT3." (PMID 40612058, 2025). "Our molecular docking results showed that the overall scores of TNF, TLR4, IL1β, and Alb when docking with four key components were all lower than –5.0 kcal/mol, which suggested that they may play an essential role in CTGO against eczema." (PMID 35907999, 2022).
esophagitis (10 papers, 2014 to 2024). An acute or chronic inflammatory disease affecting the esophageal wall. "The interleukin 1 (IL1) family pathway with its downstream effectors (IL1A, IL1R1, IL1RN, IL1B) are esophagus-specific genes and were shown in previous studies to be linked, among others, with the development and progression of acute esophagitis and BE." (PMID 35328735, 2022). "Several studies have shown that IL-1β, present in esophagitis, induces IL-6 production, driving inflammation." (PMID 35565378, 2022). "In the initiating steps during esophagitis, squamous epithelial cells secret IL-1β and IL-8, as evident by both mouse and human data." (PMID 35565378, 2022). "Further studies by Abdel-Latif et al38 observed that IL1β expression increased progressively, coincidental with NF-κB transcriptional activation, from esophagitis through BE-EAC." (PMID 35123116, 2022). "This cytotoxicity of hydrogen peroxide seemed to be related with its ability to induce IL-1β, IL-8, and IL-6, suggesting a role for classic stress signaling pathways during esophagitis and GERD." (PMID 25276052, 2014). ",32, 33, 34, 35, 36 Analysis of polymorphic variation surrounding the IL1B gene along the esophageal disease spectrum has trended toward nonsignificant associations." (PMID 35123116, 2022). "In L2-IL-1β mice, however, the inflammatory esophagitis is genetically induced and maintained not by GERD but by the constitutive expression of IL-1β in the esophagus, rendering the esophagitis refractory to PPI treatment." (PMID 27448962, 2017).
H1N1 virus infection (10 papers, 2012 to 2025). "In this study, we investigated the relationship between single-nucleotide polymorphisms (SNPs) of Interleukin-1A (IL-1A) and Interleukin-1B (IL-1B) and the susceptibility to 2009 pandemic A/H1N1 influenza (A(H1N1)pdm09)." (PMID 23927441, 2013). "In addition, the IL1B rs16944 G allele is protective against the development of severe influenza A (H1N1) virus infection (pA/H1N1 vs. ILI: p = 0.048; OR = 0.70, 95% CI: 0.50–0.98)." (PMID 26657940, 2015). "Several studies have shown that children and mice infected with H1N1 influenza, presented more severe clinical manifestations and expressed high level of IL-1β cytokine compared to the control group with mild clinical manifestations." (PMID 31196204, 2019). "Our previous study demonstrated that the swine influenza virus (SIV) infection induced NLRP3 inflammasome activation leading to the IL-1β production in primary porcine alveolar macrophages (PAMs)." (PMID 30096906, 2018). "The TNF gene was associated with disease severity, whereas IL1B and IL6 SNPs were associated with influenza A (H1N1) virus infection." (PMID 26657940, 2015). "Significantly higher levels of IL-1β and IL-6 were detected in all patients with H1N1 virus infection compared to controls." (PMID 23737648, 2013). "In conclusion, H1N1 virus infection induces an early and significant upregulation of both interleukins IL1β and IL-6 plasma expressions." (PMID 23737648, 2013). "We previously showed that the swine influenza virus (SIV) infection induced NLRP3 inflammasome-mediated IL-1β production in primary porcine alveolar macrophages (PAMs), and we were interested in examining the upstream signaling events that are involved in this process." (PMID 30096906, 2018). "In particular, IL-1β and IL-6 have been identified as markers of severity in acute lung injury during influenza A (H1N1) virus infection; IL-1β in particular has been proposed as a good early marker of the severity and progression of lung inflammation in mechanically ventilated patients." (PMID 26657940, 2015). "Therefore, this study suggests that the protective effect of hUCMSC-EVs against lung damage caused by influenza A virus (H1N1) infection may be related to the reduction in inflammatory cytokine levels of TNF-α, IL-1β, and IL-6, thereby alleviating pulmonary inflammation." (PMID 41009408, 2025). "CS exposure and H1N1 virus infection can activate NF-κB signaling pathway and NLRP3 inflammasome and promote proinflammatory cytokine (IL-6, IL-1β) release and Th17 cell differentiation." (PMID 34393799, 2021).
Helicobacter infection (10 papers, 2013 to 2025). "The regulation of IL-32 expression in response to H. pylori-infection could be weakened by using neutralizing antibodies to block IL-1β and TNF-α." (PMID 24633341, 2014). "However, more recent studies in a mouse model found that overexpression of IFN-γ inhibited gastric carcinogenesis induced by IL-1β and/or Helicobacter infection by suppressing putative gastric progenitor cell expansion and by reducing epithelial cell apoptosis via induction of an autophagy program." (PMID 28558708, 2017). "GES-1 cells and Helicobacter infection in vivo aggravate the inflammatory response by down-regulating AKT and increasing NF-κB, which induce NLRP3, pro-IL-1β, IL-1β, and IL-18." (PMID 40264171, 2025). "The analysis of the most prominent pro-inflammatory cytokines involved in Helicobacter infection (IL8, IL6, TNFα, IL1β and IFNγ) revealed that the main difference between the two conditioned media was on IFNγ, not expressed in the THP1 system." (PMID 36514982, 2022). "In order to characterize the inflammatory response across the infection, we analyzed the levels of IL-1β, IL-6, IFN-γ, CXCL5, and CXCL15, reported to be up-regulated upon Helicobacter infection in different studies." (PMID 29085807, 2017). "Upon Helicobacter infection, gastric epithelial cells produce inflammatory cytokines, such as IL-8, and inflammatory cells recruited from the bone marrow accelerate the inflammatory reaction by producing TNF-α or IL-1β." (PMID 29212456, 2017). "Moreover, overexpression of the proinflammatory IL1B or IFN-gamma under control of the parietal cell-specific H+/K+ ATPase β promoter drives gastric neoplasia development without accompanying Helicobacter infection." (PMID 38682907, 2024).
hidradenitis suppurativa (10 papers, 2016 to 2025). A chronic suppurative and cicatricial disease of the apocrine glands occurring chiefly in the axillae in women and in the groin and anal regions in men. "Tumor necrosis factor (TNF)-α, IL-1β and other cytokines promote inflammatory responses that cause many of the clinical problems associated with immune-mediated diseases, such as rheumatoid arthritis, hidradenitis suppurativa, ulcerative colitis and Crohn’s disease." (PMID 27402195, 2016). "Given the implication of the IL-1β pathway in the pathogenesis of syndromic hidradenitis suppurativa (HS), an autoinflammatory immune-mediated skin condition, the potential involvement of AIM2 was investigated." (PMID 36680007, 2023). "Th17/ILC3 lymphocytes, with high levels of IL-1β, TNF-α, IL-17 and peripheral recruitment of IL-17-producing neutrophils and Th17-cells represent the main hallmarks of hidradenitis suppurativa immune response pattern." (PMID 37484864, 2023). "Notably, the patient also presented with hidradenitis suppurativa, a chronic inflammatory skin condition involving TNF-α and IL-1β pathways." (PMID 41409927, 2025).
Hyponatremia (10 papers, 2016 to 2025). An abnormally decreased sodium concentration in the blood. "It has also been reported that CRP, IL-6, IL-1β, and neutrophil counts are associated with hyponatremia." (PMID 35356251, 2022). "Lipopolysaccharide (LPS) and inflammatory mediators (such as IL-1β, IL-6, and TNF-α) contribute to the pathogenesis of hyponatremia." (PMID 40636392, 2025). "Inflammatory cytokines, such as interleukin (IL)-1β and IL-6, have been shown to induce activation of ADH, resulting in hyponatremia." (PMID 36556138, 2022). "Because IL-6 and IL-1β are all important cytokines in the pathogenesis of SLE both in animal models and human SLE21, 22, 23, 24, there is a possibility that increased these cytokines could be implicated in the pathogenesis of hyponatremia in the patients with SLE." (PMID 27193532, 2016). "Meanwhile, the inflammation associated hyponatremia also occurred in non-malignant diseases, in which hyponatremia was correlated with neutrophil counts, CRP, IL-1β, and IL-6 levels." (PMID 33552948, 2020). "Although the accurate etiology for hyponatremia in patients with complicated appendicitis is still not identified, there is persuasive data to support a role for pro-inflammatory cytokines, such as IL-6, IL-1β, etc., in the non-osmotic release of antidiuretic hormone (ADH)." (PMID 35884054, 2022).
Impaired glucose tolerance (10 papers, 2008 to 2024). An abnormal resistance to glucose, i.e., a reduction in the ability to maintain glucose levels in the blood stream within normal limits following oral or intravenous administration of glucose. "We conclude that IL-1β is a causal driver of impaired glucose tolerance in GDM." (PMID 32080229, 2020). "Another study in patients with impaired glucose tolerance treated with simvastatin reported that addition of metformin reduced both IL-1β and IL-6 in LPS-treated peripheral blood monocytes." (PMID 32940892, 2021). "IL1β contributes to the development of impaired glucose tolerance in mice." (PMID 39519233, 2024). "The key pyroptotic protein defect in muscular dystrophy mice alleviates atrophy and improves muscle function, and the inhibition of Caspase1/GSDMD/IL-1β pathways ameliorates skeletal muscle pathology in rats with impaired glucose tolerance induced by a high-fat diet." (PMID 37720530, 2023). "In contrast to oGDM mice injected with anti-IL-1β, HFD-fed pregnant Il1bfl/flLyz2-Cre knock out mice were not protected from impaired glucose tolerance." (PMID 32080229, 2020).
kidney stone (10 papers, 2014 to 2026). "Inhibiting CaOx crystal induced renal cell pyroptosis, including downregulating the expression of NLRP3, caspase-1, IL-1β, and other related pyroptosis proteins, can reduce the risk of kidney stone formation." (PMID 39768161, 2024). "Calcium oxalate crystals activate the NLRP3 inflammasome, leading to the release of pro-inflammatory factors such as IL-1β and increased production of reactive oxygen species (ROS), triggering oxidative stress and promoting the formation of kidney stones." (PMID 41019076, 2025). "Substantial evidence indicates significant upregulation of IL-1β and IL-6 expression levels during nephrolithiasis development, particularly in calcium oxalate stone formation." (PMID 41019076, 2025). "It has been shown that CaOx crystals induce an inflammatory response through dendritic cell secretion of Il–1β, inflammasomes are involved in kidney stone pathogenesis and urine Il–6 levels are increased in patients with kidney stones." (PMID 26448465, 2015). "Given the importance of renal immune response in the pathophysiology of kidney stones, we investigated the correlations between miR-155 and important proinflammatory cytokines: IL-1β, IL-6, and TNF-α, a chemokine (RANTES) in the urine sediment." (PMID 25197634, 2014). "Natural active ingredients prevent and treat kidney stones by modulating inflammatory and oxidative stress related pathways, the mechanism of which involves inhibition of the release of pro-inflammatory factors such as IL-1β, IL-6, TNF-α etc." (PMID 41019076, 2025). "In this study, Hyp intervention exhibited a notable decrease in the levels of IL-1β, IL-6, IL-8, and TNF-α in cell and rat models, suggesting the anti-inflammatory role of Hyp in nephrolithiasis." (PMID 36942317, 2023). "Repressing the release of pro-inflammatory cytokines, such as IL-1β, TNF-α, IL-6, and oxidative stress mediators, such as ROS, and MDA, can markedly relieve pain and cell apoptosis in kidney stones." (PMID 38154105, 2023). "Calcium oxalate crystals, a key component in kidney stones, induce an inflammatory response by activating the NLR family pyrin domain containing 3 inflammasome (NLRP3), resulting in the release of pro-inflammatory cytokines IL-1β and IL-18." (PMID 38281018, 2024). "For clarifying the effects of Hyp on oxidative stress injury and inflammatory response in rats with renal calculi, we measured the levels of oxidative stress-related substances (MDA, LDH, ROS, and SOD) and inflammatory factors (IL-1β, IL-6, IL-8, and TNF-α) in the kidney tissue of rats." (PMID 36942317, 2023).
leukopenia (10 papers, 2015 to 2024). "Intriguingly, both WT IL-1β and CD8α ALN-1 elicit leukopenia, which we found is primarily due to a reduction in circulating lymphocytes as the level of neutrophils remains unaltered." (PMID 32714571, 2020).
leukoplakia (10 papers, 2012 to 2025). A white patch or plaque on a mucous membrane that cannot be characterized clinically or pathologically as any other disease. "Loss of IL-1β and 8 in potentially malignant disorders, as leukoplakia and OLP, might suggest the start of a malignant transformation process." (PMID 35048001, 2021). "In biopsied tissues of OSCC and leukoplakia, IL-1β levels rose progressively as tissues advanced through the stages of malignant transformation." (PMID 41440367, 2025). "Lower IL-1β positive cells were observed in leukoplakias (224.60 ± 161.05 cells/field), OLP (111 ± 101.752 cells/field), and OSCC (132.07 ± 121.951 cells/field)." (PMID 35048001, 2021). "In the leukoplakia sample, IL-1β staining was modestly higher (the frequency of IL-1β-positive cells was 78.4% ± 7.3%)." (PMID 26831400, 2016). "Patients with oral leukoplakia had significantly lower concentrations of salivary IL-1β compared to control group (p≤0.05)." (PMID 21743397, 2012). "This might suggest that loss of IL-1β implies pyroptosis reduction, favoring cell proliferation, observed in OLP and leukoplakia, which is a determining fact of OSCC pathogenesis." (PMID 35048001, 2021). "- Expression of IL-1β and 8 are present in both leukoplakia and OLP, although variable." (PMID 35048001, 2021). "In opposition to earlier reports, a recent study confirmed a decrease in the expression of IL-1β and IL-8 in OSCC compared to OLP and leukoplakia." (PMID 41440367, 2025). "However, staining of IL-1β was particularly prominent in the abundant epithelial cytoplasm in SCC samples (the frequency of positive cells was 91.5% ± 2.9%), where it was significantly higher than in normal and leukoplakia samples (P < 0.05)." (PMID 26831400, 2016).
Lyme disease (10 papers, 2006 to 2025). Lyme disease (named after the towns in the USA where the disease was first identified) is a bacterial infection caused by Borrelia burgdorferi. "It should be noted that the latest research concerning Lyme borreliosis indicated that the EFR3A protein is engaged in the regulation of IL-1β responses in PBMCs (one of the strongest associations with IL-1β responses upon Bb stimulation of these cells)." (PMID 40305161, 2025). "Further, acetate supplementation was effective at reversing brain microglia activation and reduced IL-1β levels, suggesting that treatment may reduce the pathologic sequelae in brain associated with Lyme neuroborreliosis." (PMID 23134838, 2012). "In comparison to the control group, Lyme borreliosis patients presented with higher levels of IL-1β and IL-8, with some extreme outliers in IL-6." (PMID 31366164, 2019). "IL-1β is a potent proinflammatory cytokine, and thought to play a key role in the pathogenesis of Lyme arthritis, a common manifestation of Borrelia burgdorferi infection." (PMID 23148704, 2012). "Cells from humans bearing the NOD2 frameshift mutation produced less IL-1β when exposed to B. burgdorferi, indicating that this PRR is also important in Lyme disease." (PMID 23148704, 2012). "The concentrations of IL-1β, IL-1Ra, IL-6, sIL-6Rα, sgp130, and IL-15 in the serum of patients with Lyme disease were significantly higher than those in the serum ofcontrol group." (PMID 16864901, 2006). "TLR2 expression in relation to expression and production of cytokines and their regulators suggestsa role of this receptor in enhanced IL-6- and inhibition of IL-1β-mediated reactions in patients with Lyme disease." (PMID 16864901, 2006). "The transcript levels of several important cytokines and chemokines that have been reported to contribute to Lyme disease progression, such as IL-10, IL-1β, TNF-α, and CCL2, were upregulated in the WT- but not MT-infected tissues, which was validated by qRT-PCR." (PMID 38011206, 2023). "The concentration of IL-1β is higher in Lyme borreliosis patients." (PMID 31366164, 2019). "IL-1β as a major cytokine induced by inflammasome activation, was also upregulated in patients with carcinoma (Group 1) in addition to Lyme borreliosis patients with neurological diseases (Group 3), and in patients with multiple additional infections (Group 4)." (PMID 31366164, 2019). "Apart from IL-1Ra, anti-IL-1β antibodies like Canakinumab might be useful for treatment of Lyme disease since these antibodies express a long half-life in humans." (PMID 23148704, 2012). "In contrast, IL-1β has ability to enhance the IL-6 production by immune cells.Furthermore, increased sIL-1RII production by these cells, acting as inhibitor for IL-1β, may lead to decrease its activity in patient with Lyme disease." (PMID 16864901, 2006). "In the unstimulated samples, the concentrations of cytokines in patients with Lyme neuroborreliosis were comparable with references, except interferon (IFN)-α, interleukin (IL)-17A, IL-1β and IL-8, which were all significantly below the references." (PMID 34041044, 2021). "In the present study, TLR2 expression and productionof IL-1β and IL-6 as well as their natural regulators (sIL-1RII, IL-1Ra and sIL-6Rα, sgp130, resp) by PMN of peripheral blood in patients with Lyme disease were examined." (PMID 16864901, 2006). "In the present study, TLR2 expression in relation to expression and production of IL-1β, IL-6, as well as their natural regulators (sIL-1RII, IL-1Ra and sIL-6Rα, sgp130, resp) production by PMN of peripheral blood in patients with Lyme disease were estimated." (PMID 16864901, 2006). "Bulk RNA-seq analysis of infected mouse skin tissues further show that cheA1mut fails to elicit mouse tnf-α, il-10, il-1β, and ccl2 expression, four important cytokines for Lyme disease development and B. burgdorferi transmigration." (PMID 38011206, 2023).